SOCS3 (suppressor of cytokine signaling 3)
Diseases named in the same sentence as SOCS3 in open-access papers (continued):
Sharing a sentence is not in itself a finding about the gene and the disease.
hepatocellular carcinoma (continued). "This was found to cause lysis in hepatocellular carcinoma cell lines, but not in normal liver cells indicating that further experimental studies on SOCS3 could increase its future applicability as a cancer cell specific anti-cancer agent." (PMID 28603644, 2017). "Suppressor of cytokine signaling 3 (SOCS3) plays crucial roles in JAK/STAT signaling pathway inhibition in hepatocellular carcinoma (HCC)." (PMID 26393582, 2015). "Similarly, SOCS3 may also be involved in the suppression of tumour growth and metastasis of several malignancies including lung cancer, hepatocellular cancer, and head and neck squamous cell carcinoma." (PMID 20433750, 2010). "From two novel proteins associated with hepatocellular carcinomas in man, suppressors of cytokine signaling type 3 (SOCS3) and collagen-I, a non-significant 2-fold elevation of SOCS3, were found and a 7-fold, significant down-regulation of collagen-I was observed." (PMID 15566568, 2004). "This epigenetic modification silences SOCS-3, thus leading to the constitutive activation of STAT3 in hepatoma cells." (PMID 37941812, 2023). "SOCS3 has been reported to negatively regulate TGF-β1 production and liver fibrosis in hepatocellular carcinoma or hepatitis C virus (HCV) infection." (PMID 37253066, 2023). "For example, SOCS1 and SOCS3 expressing oncolytic adenovirus (CN305 (AdCN305)-SOCS3) or recombinant, cell-permeable proteins has been shown to efficiently control aberrant STAT signaling in hepatocellular carcinoma." (PMID 35844493, 2022). "It was previously found that the expression of SOCS3 in hepatocellular carcinoma tissues and cell lines was negatively correlated with EZH2 and depended on its promoter methylation status through TCGA hepatocellular carcinoma data analysis." (PMID 34868904, 2021). "Methylation silencing of SOCS3 increases the IL-6/JAK/STAT3 and FAK phosphorylation in human hepatocellular carcinoma." (PMID 28228755, 2017). "Furthermore, SOCS3 overexpression considered as a potential therapeutic target for TNBC and hepatocellular carcinoma, aligning with our finding." (PMID 39507529, 2024). "In hepatocellular carcinoma, the overexpression of C1QTNF1-AS1 was shown to regulate miR-221-3p and suppressor of cytokine signaling 3 (SOCS3), leading to a decrease in cancer cells’ proliferation, migration, and invasion, while also inducing apoptosis via the JAK/STAT signaling pathway." (PMID 37489459, 2023). "Hence, we retrospectively selected 74 hepatocellular carcinoma cases and performed immunohistochemical analysis for PD-L1, CD4, CD8, CD276 and SOCS3 for each paraffin-embedded block." (PMID 32742491, 2020). "We establish, based on quantitative measurements obtained for the hepatoma cell line Huh7.5, an ordinary differential equation model for IFNα signal transduction that comprises the feedback regulators STAT1, STAT2, IRF9, USP18, SOCS1, SOCS3, and IRF2." (PMID 32696599, 2020). "Recent data indicate that IL-6 may interfere with IL-27 functions due to the induction of SOCS3 expression, which inhibits IL-27-mediated STAT signaling, in hepatocellular carcinoma cells." (PMID 29020964, 2017). "Previous studies showed that suppressor of cytokine signaling 3 (SOCS3) protein is associated with incidence and progression of hepatocellular carcinoma (HCC); however, the association between the genetic polymorphism of SOCS3 gene and HCC remains unknown." (PMID 26447993, 2015). "The reverse correlation found between hypermethylation and silenced SOCS-3 was tested in the second exon (gene body), not in the promoter region, and hypermethylation of SOCS-1 promoter was found in certain hepatocellular carcinoma cell lines." (PMID 30987235, 2019).
diabetes (45 papers, 2008 to 2025). "Thus, to further assess the effects of diabetes on IL-6R-associated transcriptional activation, SOCS3 expression in the skin was assessed." (PMID 31073533, 2019). "Furthermore, even though a few other CpGs were found to be associated with alcohol consumption, diabetes or cancer, such as cg18181703 in SOCS3 and cg26470501 in BCL3, most of them also showed associations with smoking exposure in our analyses." (PMID 28303888, 2017). "In addition, 4 of the 48 smoking-associated CpGs, including 2 diabetes-associated sites (cg18181703 in SOCS3 and cg26470501 in BLC3), were also associated with prevalent cancer." (PMID 28303888, 2017). "Using a large virtual screen comprised of current diabetes treatments as well as general ligand libraries the authors identified a number of novel binders of SOCS3, primarily for the SH2 domain, which would enable the inhibition of SOCS3’s activity." (PMID 39676878, 2024). "miR‐185 is another miRNA that directly targets the SOCS3 gene by binding to its 3′‐UTR to prevent β‐cell dysfunction in diabetes conditions." (PMID 37329278, 2023). "More importantly, this study laid the foundation for the study of the mechanisms of progesterone and SOCS3 gene on T2DM; however, further multicenter prospective studies are needed to determine the exact underlying mechanisms of diabetes development." (PMID 34565450, 2021). "In summary, our study identified that nicotine-provoked SOCS3-mediated AdipoR1 ubiquitination is a key mechanism of APN resistance in diabetes with nicotine." (PMID 34006831, 2021). "Found to be significantly downregulated in diabetic patients and mouse models, the miR-185 levels are directly correlated with blood glucose concentration and inversely correlated with the SOCS3 levels in diabetes patients." (PMID 29535681, 2018). "Some drugs used to treat diabetes or DR, such as statins, enalapril, and tazones, decrease SOCS3 and STAT3 expression in diabetic animals." (PMID 29318137, 2017). "Taken together, these findings demonstrated that miR-185 played a protective role in diabetes, at least, in part due to directly inhibiting SOCS3 expression." (PMID 25658748, 2015). "The data of Bao and our results show, that these different pathways can be in the background of the same phenotype, as miR-185 is suggested to be related to diabetes mellitus via two different (SOCS3 and WFS1) targets." (PMID 26426397, 2015). "In conclusion, this study revealed a functional and mechanistic link between miR-185 and SOCS3 in the pathogenesis of diabetes." (PMID 25658748, 2015). "Upregulation of miR-185 expression effectively suppressed SOCS3 expression at both mRNA and protein levels, whereas, downregulation of miR-185 induced SOCS3 expression, suggesting a potential inverse relevance between miR-185 and SOCS3 in diabetes." (PMID 25658748, 2015). "It is possible that the sensitized STAT3 phosphorylation accompanied by reduced SOCS3 activation in DM myocytes is a dysregulation compensating for other diabetes related alterations in cell signaling in skeletal muscle." (PMID 22761857, 2012). "SOCS3, a key protein in many pathological events, such as diabetes and immune disorders, has emerged as the most essential regulator in the inhibition of the Janus kinase (JAK)-signal transducer and activator of transcription (STAT) pathway among the SOCS family." (PMID 36145200, 2022). "Finally, the direction of association for CPT1A, ABCG1, SOCS3, TXNIP and SREBF1 was consistent with that reported in the literature for MetS and/or diabetes." (PMID 34780523, 2021). "Thus, the regulation of the PERK/Nrf2 pathway by baicalein verified in this study, together with the regulation of SOCS3 and other mechanisms, contributes to the improvement of insulin resistance for the prevention and treatment of diabetes." (PMID 32019168, 2020).
diabetes (continued). "Suppresser of cytokine signaling 3 (SOCS3) is an established negative feedback regulation transcription factor associated with tumor, diabetes mellitus, inflammation and anaphylaxis." (PMID 32127783, 2020). "The exact mechanism of interplay between IL-6, STAT3, and SOCS3 at an organismal level during diabetes is likely complex; thus, it was of interest to determine if hyperglycemia itself might mediate altered IL-6R function in keratinocyte culture." (PMID 31073533, 2019). "Another explanation for the increased sensitivity of SOCS-3 transgenic mice to MLDSTZ-induced diabetes is that SOCS-3 overexpression could obstruct normal β-cell functioning, for instance, by interfering with JAK/STAT-dependent insulin signaling." (PMID 27242781, 2016). "Moreover, we observed that miR-185 level was inversely correlated with SOCS3 expression in diabetes patients." (PMID 25658748, 2015). "Those include SOCS3 which in cell culture is β-cell protective, however, by curbing protective STAT3 signaling in vivo, seemingly is pathogenic as detected using a β-cell-specific knockdown during STZ-induced diabetes." (PMID 26793108, 2015). "Expression of SOCS3 was much higher in patients with diabetes than those with IFG/IGT or NGT." (PMID 25658748, 2015). "Thus taken together, dysregulated SOCS3 expression appears to be important for the development of insulin resistance and type 2 diabetes mellitus." (PMID 24886706, 2014). "This study aimed to evaluate the roles of SOCS-1 and SOCS-3 in the pancreas, liver, and kidney and to explore the involvement of the JAK/STAT pathway in the molecular mechanisms underlying their effects on inflammation and apoptosis, as well as organ injury in a diabetes mellitus (DM) model." (PMID 39968090, 2025). "The miR-19a-3p/SOCS3 axis may there be a potential therapeutic target for diabetes." (PMID 36527500, 2023). "However, one report examined whether β-cell-specific SOCS-3 expression could protect B6 mice from multiple low-dose streptozotocin-induced diabetes development." (PMID 27242781, 2016). "Moreover, they also demonstrate that dysregulation of this aspect of SOCS3 function may be integral to the development of several disorders, including diabetes, cancers and multiple chronic inflammatory and immune diseases." (PMID 24886706, 2014). "Islets from Socs3−/− mice were pre-cultured with exogenous SDF-1 and transplanted underneath the kidney capsule of C57BL/6 mice with streptozotocin-induced diabetes." (PMID 37400916, 2023). "Hence, the miR-19a-3p/SOCS3 axis may also become a potential therapeutic target for diabetes." (PMID 29535681, 2018). "Here, we provided new evidence that SOCS3 and STAT3 gene expression were also elevated in the late period of diabetes, as the present study was conducted for 32 weeks." (PMID 29318137, 2017). "Recent researches showed that upregulation of SOCS3 expression downregulated subsequent JAK/STAT signaling pathway, thereby reducing the destructive of beta-cell cytotoxic cytokines in diabetes." (PMID 29311988, 2017). "In the early-middle stages of diabetes, the levels of STAT3 and SOCS3 in the retinas are increased." (PMID 29318137, 2017). "In mice, however, β-cell specific overexpression of SOCS3 failed to protect against MLD-STZ induced diabetes." (PMID 27542279, 2016). "Consistently, a negative correlation between miR-185 and SOCS3 was observed in plasma samples of patients with diabetes." (PMID 25658748, 2015). "While the role of miR-450a on the regulation of endocrine function or in diabetes is not clear to date, miR-185 plays an important role in the regulation of insulin secretion and β cell growth via targeting suppressor of cytokine signaling 3 (SOCS3)." (PMID 27153060, 2016). "However, overexpression of SOCS3 could increase islet graft survival in BALB/c mice with alloxan-induced diabetes but not in NOD mice." (PMID 37400916, 2023). "It is not yet known whether SOCS-3 transgenic expression impacts spontaneous diabetes." (PMID 27242781, 2016).
diabetes (continued). "SOCS3 and PTP1B levels were not significantly increased in the diabetic subjects, but it is well-established that patients with type 2 diabetes mellitus have defects in the insulin signaling cascade that stimulate GLUT4 translocation." (PMID 22114711, 2011).
asthma (40 papers, 2011 to 2025). "Recently, our study found that methyl CpG binding domain protein 2-mediated Th17 differentiation in severe asthma is associated with IRF4 and SOCS3 expression, providing novel insight into epigenetic regulation and target for treatment in severe asthma." (PMID 34566492, 2021). "The augmenting of SOCS3 expression in T cells has been associated with asthma severity." (PMID 31565031, 2019). "Another study utilized SOCS3 siRNA intranasal therapy in an asthma mouse model, resulting in decreased eosinophil counts, normalization of high reactivity to methacholine, improved mucus secretion, and reduced airway remodeling." (PMID 38396957, 2024). "In another study involving an asthma mouse model, matrine was found to inhibit SOCS3 expression, significantly reducing inflammatory cell infiltration, goblet cell differentiation, and mucus production in a dose-dependent manner." (PMID 38396957, 2024). "SOCS3 has been shown to have an important role in regulating the onset and maintenance of Th2-mediated allergic and atopic diseases, such as AD and asthma." (PMID 38975347, 2024). "In fact, SOCS3 transgenic mice overexpressing SOCS3 in T cells show increased Th2 responses and multiple pathological features typical of asthma in an airway hypersensitivity model system." (PMID 38975347, 2024). "Its implication in immune diseases, including allergic dermatitis and asthma, is notable, as overexpression of SOCS3 in T cells and B cells is correlated with Th2 reactions and blood IgE concentration." (PMID 38396957, 2024). "While this study focused on asthma, both AR and asthma fall under the category of united airway disease, making the findings relevant to the study of SOCS3 and AR." (PMID 38396957, 2024). "For example, SOCS3 can suppress the induction and development of rheumatoid arthritis, and SOCS3 is also closely related to the progression of asthma." (PMID 36690663, 2023). "Alveolar macrophage-derived EVs containing SOCS1 and SOCS3 can inhibit asthma pathogenesis when taken up by AECs." (PMID 36316787, 2022). "Sun and others demonstrated the inhibitory effect of SOCS3 on differentiation of Th17 cells in an asthma model." (PMID 34760922, 2021). "We discovered higher STAT3 expression and lower SOCS3 expression in the lung tissue of asthma patients compared with that of healthy controls (HCs) and observed a correlation between STAT3 expression or SOCS3 expression and the expression of IL-17A protein." (PMID 34760922, 2021). "In a study, MBD2 downregulated the SOCS3 expression and promoted the differentiation of Th17 cells in severe asthma, showing its involvement in Th17 mediated neutrophilic predominant severe asthma." (PMID 35096261, 2021). "The level of SOCS3-rich EVs was decreased in patients with asthma, as well as in murine asthma models." (PMID 33915715, 2021). "Our analyses in the human lung tissue of the expression of STAT3 and SOCS3 further convinced us that STAT3 and SOCS3 are involved in asthma." (PMID 34760922, 2021). "Simultaneously, the expression of SOCS3 protein decreased in both mouse models of asthma compared with that in the control group." (PMID 34760922, 2021). "Results of an in vitro experiment suggested that inflammatory cytokines are responsible for the decrease in SOCS3 secretion and contribute to defects observed in asthma." (PMID 33915715, 2021). "The role of STAT3 and SOCS3 in asthma has been discussed in relation to the T2-mediated allergic response." (PMID 34760922, 2021). "The correlation between the expression of STAT3 or SOCS3 and airway inflammation indicated that STAT3 and SOCS3 are involved in asthma." (PMID 34760922, 2021). "The STAT3-positive area increased in the lung tissue of asthma patients compared with that in HCs, whereas SOCS3 expression decreased in the lung tissue of asthma patients." (PMID 34760922, 2021).
asthma (continued). "A strong correlation between SOCS3 expression and asthma severity and serum IgE levels in allergic patients has been reported, which is in accordance with our findings in mouse models." (PMID 34760922, 2021). "There is still lack of study in effects of ozone exposure on SOCS3, and few scholars have focused on the role of STAT3 and SOCS3 in the mechanism of action of T2-low asthma and corticosteroid resistance." (PMID 34760922, 2021). "The induction of severe asthma in SOCS3 knockout mice increased IL-17 levels and also stimulated its differentiation." (PMID 31565031, 2019). "Increased SOCS3 and IL-6 expression in atopic conditions such as asthma, rhinitis, dermatitis, conjunctivitis and food allergies play pivotal role in the development of atopic conditions." (PMID 31251775, 2019). "SOCS3 expression has been positively correlated with asthma severity and serum IgE levels; moreover, a successful animal model has been tested to demonstrate SOCS3 involvement in asthma modulation." (PMID 25764157, 2015). "Our group has demonstrated that it is present in lungs from subjects with asthma, and is capable of inducing and regulating SOCS3 expression in human eosinophils." (PMID 25764157, 2015). "Previously, we have demonstrated that eosinophils purified from peripheral blood from asthma patients express high levels of suppressor of cytokine signaling 3 (SOCS3)." (PMID 25764157, 2015). "Because miRNAs are now recognized as key regulatory elements in gene expression, we determined which miRNAs had modified their expression following SOCS3-siRNA therapy in the asthma mouse model using microarray analysis." (PMID 24637581, 2014). "In patients with asthma and atopic dermatitis, the expression levels of SOCS3 transcripts in T cells are closely correlated with serum IgE levels and disease severity." (PMID 24637581, 2014). "In fact, T cell treatment with SOCS3-siRNA has been demonstrated to suppress the development of allergic inflammation in another murine model of asthma." (PMID 24637581, 2014). "In our model of asthma SOCS3-siRNA treatment produce also a decreased expression in IL-5, IL-13, and IL-4." (PMID 24637581, 2014). "It was shown that the expression level of SOCS-3 was increased in asthma and correlated with the pathology of this TH2-mediated allergic disease." (PMID 24138793, 2013). "The genetic-gene expression network identified the SOCS3 pathway as one of the key drivers of asthma." (PMID 23209423, 2012). "As elevation of serum IgE is a characteristic of patients with NAEB and asthma, we determined the correlation between serum IgE and the expression of SOCS3." (PMID 21765854, 2011). "We also found that SOCS-3 expression in blood eosinophils from patients with asthma and NAEB was correlated with serum IgE levels (r = 0.5, P < .03)." (PMID 21765854, 2011). "The transcriptional downregulation of SOCS3 has been observed in asthma and COPD patients." (PMID 35163689, 2022). "STAT3 and SOCS3 appeared to be involved in asthma pathogenesis in mouse models and asthma patients." (PMID 34760922, 2021). "SOCS3 loaded EVs from AMs may play an important role in the pathogenesis of asthma and synthetic SOCS3 encapsulated liposomes treated in cells and mouse model of allergic asthma showed attenuation of cytokine release and airway inflammation, respectively." (PMID 34414402, 2021). "However, few studies have paid attention to the potential role of SOCS3 in corticosteroid resistance in an asthma model closely related to Th17 cells." (PMID 34760922, 2021). "Besides, the suppressor of cytokine signaling-3 (Socs3) regulates the interrelation between Th1 and Th2 cells in asthma." (PMID 33781317, 2021). "Therefore, siRNA technology has been used again to better understand the role of SOCS3 in human eosinophils, as central players in asthma pathogenesis." (PMID 25764157, 2015).